NEK1 (NIMA related kinase 1)
Diseases named in the same sentence as NEK1 in open-access papers (continued):
Sharing a sentence is not in itself a finding about the gene and the disease.
papillary thyroid cancer (1 paper, 2020). "Furthermore, this work, demonstrated for the first time a high specificity and sensitivity of over-expression of NEK1 in classical and follicular variants of papillary thyroid cancer and NEK3 in tall-cell papillary thyroid cancer." (PMID 31906878, 2020).
prostate adenocarcinoma (1 paper, 2020). "We analyzed mRNA expression of both NEK1 and YAP1 in prostate adenocarcinoma (PRAD) and head and neck squamous cell (HNSC) carcinoma patients from TCGA datasets using the UALCAN online platform." (PMID 33297404, 2020).
retinitis pigmentosa (1 paper, 2024). Retinitis pigmentosa (RP) is an inherited retinal dystrophy leading to progressive loss of the photoreceptors and retinal pigment epithelium and resulting in blindness usually after several decades. "Furthermore, variants in NEK1 and C21ORF2 are causative for both ALS and retinitis pigmentosa." (PMID 38658168, 2024).
skin cancer (1 paper, 2023). "COSMIC analysis reveals NEK1 mutations to be highly associated (greater than 7% of tissues with NEK1 mutations) with endometrial, liver, ovarian, pancreatic, and skin cancers, with 24.82% of mutations being missense substitutions." (PMID 37046733, 2023).
thyroid (1 paper, 2020). "The present study also aimed to investigate a possible role for NEK1, NEK3, and NEK5 in thyroid malignancy, and analyze their potential as diagnostic and prognostic markers." (PMID 31906878, 2020). "Here, we studied the expression of NEK1, NEK2, NEK3, and NEK5 in different types of normal and malignant tissues, using tissue microarray analysis, and identified NEKs as potential markers in thyroid malignancy." (PMID 31906878, 2020). "Regarding mainly the expression of NEK1 and NEK3 in DTC, our results indicate that these NEKs may have an important role in thyroid malignancies, allowing to identify malignancy and aggressiveness features of DTC cases." (PMID 31906878, 2020).
cancer (22 papers, 2011 to 2026). A tumor composed of atypical neoplastic, often pleomorphic cells that invade other tissues. "NIMA-related kinase 1 (NEK1), a serine/threonine kinase implicated in cell cycle regulation and DNA damage response, has been associated with tumorigenesis in various cancers, yet its specific role in OV pathogenesis remains elusive." (PMID 42193091, 2026). "For both cancer-predisposition genes NEK1 and TBK1, using gnomAD showed a much-improved significance level, compared with that using the study-specific control summary counts." (PMID 35545612, 2022). "The mechanisms underlying the association of Nek1 with the radiation response in cancer cells and the response to radiation therapy remain to be defined." (PMID 32429458, 2020). "Our results indicate that elevated levels of Nek1 were associated with an increased rate of local or distant failure, as well as with impaired cancer-specific and overall survival in univariate analyses and for most endpoints in multivariable analyses." (PMID 32429458, 2020). "NEK1 -/- cells also exhibited other qualities of cancer cells, including loss of contact inhibition to allow for multilayered growth, and the ability to grow at higher saturation density than wild type cells." (PMID 21214959, 2011). "Disruption of these interactions, whether through mutations in NEK1 or its partners, leads to genomic instability and cancer progression." (PMID 41154634, 2025). "In pancreatic cancer, NEK1 is similarly associated with poor prognosis, suggesting that it may play a role in the aggressive nature of this cancer." (PMID 41154634, 2025). "The fact that Nek1 levels determine cellular tolerance to DNA-damaging agent treatment might begin to explain the underlying mechanism of chemo-resistance observed in cancer cells." (PMID 24970796, 2014). "To help determine whether the p16INK/p19ARF pathway, which is commonly affected in cancers, is downregulated in tumors mediated by Nek1 deficiency or inactivation, we examined p19ARF in NEK1 -/- cells." (PMID 21214959, 2011). "We suggest that repeated injuries over time may need to accumulate in order to manifest gross chromosomal abnormalities and cancers late in the life of a NEK1-deficient animal, as in the life of an ATM-deficient animal." (PMID 21214959, 2011). "Studying the level of NEK1 expression in different human cancers will help to determine whether chromosome instability observed in these cancers can be attributed to loss of NEK1 activity, and whether NEK1 could be an important target for cancer treatment." (PMID 21214959, 2011). "In terms of cancer potential implications, the expression of NEK1 and YAP1 proteins was found to be increased and correlated in several cancers." (PMID 33297404, 2020). "We propose that the TLK1>NEK1>YAP1 axis is a key determinant for cancer progression, particularly during the process of androgen-sensitive to -independent conversion during progression to mCRPC." (PMID 33297404, 2020). "Analyses of cancer Protein Atlas and TCGA expression panels revealed a link between activated NEK1 and YAP1 expression and several YAP transcription targets." (PMID 33297404, 2020). "Overall, these data suggest NEK1 increases YAP1 level by reducing YAP1 protein turnover rate in different cancers." (PMID 33297404, 2020). "These novel findings are discussed in the context of a possible therapeutic exploration of NEK1 in combination with chemotherapeutic agents leading to chemosensitization in cancer cells." (PMID 28710492, 2017). "While inhibiting NEK1 can sensitize cancer cells to radiation by crippling their DNA repair capacity, this strategy could have unforeseen consequences given its protective role in the nervous system." (PMID 41154634, 2025).
cancer (continued). "We do this by evaluating the 11 NEK family kinase gene expression associations with patients’ overall survival (OS) from various cancers using the Kaplan–Meier Online Tool (KMPlotter) to correlate the relationship between mRNA expression of NEK1-11 in various cancers and patient survival." (PMID 37046733, 2023). "Only a few data are available on a prognostic or predictive value of Nek1 in cancer." (PMID 32429458, 2020). "Conversely, data from those two studies suggest that there may be positive feedback between VHL and NEK1 and a potential pathway for cancer and ciliopathy research." (PMID 32294979, 2020). "Taken together, our data support a role for NEK1 in repair of DNA double-strand breaks, including the Fanconi pathway, and given that NEK1 is up-regulated in a number of human cancers suggests targeting NEK1 as a therapeutic strategy in combination with ICL-forming agents." (PMID 28710492, 2017). "Therefore, to provide increased support for the idea of targeting NEK1 kinase activity with inhibitors as a cancer therapy we further investigated the role of NEK1 in the DNA damage response after cisplatin treatment." (PMID 28710492, 2017). "We hypothesized therefore that NEK1 +/- kat2J mice should be prone to develop cancers spontaneously." (PMID 21214959, 2011). "Therefore, we hypothesise that NEK1/4/6/7/8/9/11 may play a cancer-promoting role in STAD via Tregs." (PMID 38706902, 2024). "In cancers, NEKs such as NEK1, NEK2, NEK6, and NEK11 promote genome instability and tumor progression, while others, like NEK1, paradoxically offer opportunities for radiosensitization." (PMID 41154634, 2025). "Our bioinformatics analysis suggested a link between NEK1 and YAP1 in different cancers; the YAP1 protein is also abundant in high grade PCa tumors despite the progressive downregulation of YAP1 mRNA expression." (PMID 36979713, 2023). "A strong C21ORF2 band was detected in NEK1 precipitates from extracts of ARPE-19 cells and vice versa, and similar results were obtained in the cancer cell lines HeLa, HEK293, and U2-O-S." (PMID 37188479, 2023). "The objective of the present study was to understand the involvement of four members of the NEK family (NEK1, NEK2, NEK3 and NEK5) in different types of cancers by analyzing differential expression profiles through tissues microarray (TMA) assays." (PMID 31906878, 2020). "We propose that the signaling of TLK1>NEK1-mediated YAP phosphorylation and stabilization contributes not only to PCa progression, but also many other cancers." (PMID 33297404, 2020). "Significant increases in the protein expression levels of NEK1, NEK2, NEK3 and NEK5, were found in colon and lung in the normal vs. cancer tissues." (PMID 31906878, 2020). "This suggests that, in vivo, J54 may also modulate the proliferation of cancer cells, a property that we attributed earlier to the TLK1>NEK1>YAP1 axis that largely affects the contact inhibition features (mechano-transduction) of the cells." (PMID 40227796, 2025). "This suggests that, in vivo, J54 may modulate also the proliferation of cancer cells, a property that we attributed earlier to the TLK1 > NEK1 > YAP1 axis, largely affects the contact-inhibition features (mechanotransduction) of the cells." (PMID 36497211, 2022). "Our bioinformatics analyses also suggested a link between NEK1 and YAP1 in different cancers." (PMID 33297404, 2020). "Note, however, that RWPE1 (normal prostate) cell line was insensitive to J54, suggesting that J54 may be a more targeted anti-cancer agent, or it is possible that the TLK1>Nek1 axis remains critical even for CRPC cells." (PMID 32905878, 2020). "These modules contained several cancer regulators such as Intraflagellar Transport (IFT) complex proteins (IFT74, IFT88), BBSome complex proteins (BBS2, BBS7, BBS9, BBS12), exocyst complex components (EXOC3, EXOC4, EXOC6B, EXOC7, and EXOC8), TTC8, TTC21B, EVC, and NEK1." (PMID 40700427, 2025).
cancer (continued). "The relation between NEK1 deficiency and kidney development has already been demonstrated, as shown briefly in this review, but whether it is related to cancer development requires further investigation, for example, by assessing the dynamics of the interaction between CTNNB-1 and NEK1." (PMID 32294979, 2020). "Importantly, only NEK1 (beside NEK10 which is not elevated in cancer) is a dual-specificity kinase." (PMID 36979713, 2023). "Indeed, in the present study, we observed that the attenuation of Nek1 in HeLa and HCT-15 carcinoma cells does not interfere with the ability to induce a G2/M arrest." (PMID 32429458, 2020).
tumor (20 papers, 2011 to 2026). "NEK1 also displays potential as a prognostic marker, with higher NEK1 expression levels being associated with more aggressive tumor behavior." (PMID 41154634, 2025). "Our results about the association of Nek1 with the clinical outcome, its impact on clonogenic survival and tumor growth in vivo indicate the protein to represent a valuable target for radiation sensitization." (PMID 32429458, 2020). "In contrast, fractionated irradiation of Nek1 KD tumors caused a significant (p < 0.001) reduction of tumor volume within the first days after irradiation and a subsequent growth retardation compared to non-irradiated animals." (PMID 32429458, 2020). "Experiments using a complementary technique, FACS analysis in human U2OS tumor cells with stable knock-down of NEK1 expression, showed that NEK1 deficiency, not only the specific NEK1/kat2J mutation, leads directly to acquisition of the polyploid phenotype." (PMID 21214959, 2011). "Insufficient Nek1 expression might result in loss of critical cells at critical time and leads to organ dysfunction or tumor formation." (PMID 24970796, 2014). "A critical challenge will be to develop strategies that can selectively inhibit NEK1 in tumor tissues or to identify a therapeutic window where the benefits of radiosensitization outweigh the risks of neurotoxicity." (PMID 41154634, 2025). "By knocking down NEK1 expression, researchers observed increased sensitivity of cervical cancer cells to radiation-induced DNA damage, effectively delaying tumor growth in vivo." (PMID 41154634, 2025). "Expectedly, depleting LINC00883 yielded tumor-suppressive and anti-chemoresistance effects on U251 cells by increasing miR-136 and inhibiting NEK1." (PMID 35083134, 2021). "Nek1 is part of a 12-gene tumor score to predict progression of non-invasive to muscle-invasive bladder cancer and up-regulation correlated with adverse prognosis in pancreatic cancer." (PMID 32429458, 2020). "We identified 28 patients (37.8%) with increased Nek1 expression (weighted score: WS > 6) and 46 patients (62.2%) with low Nek1 expression in tumor biopsy samples (WS ≤ 6)." (PMID 32429458, 2020). "One alteration in these tumors that caught our attention was the 3 Mb loss in chromosome 4, which comprise at least three genes relevant for tumor suppression: NEK1, POSH and ANX10A." (PMID 26979459, 2016). "We report here that Nek1 is highly expressed in RCC tumor and cultured RCC cells compared to that of normal renal tubular epithelial cells (RTE)." (PMID 24970796, 2014). "In this communication, we have reported that elevated Nek1 protein expression in RCC tumor and cultured RCC cells compared to that of normal RTE." (PMID 24970796, 2014). "To examine this possibility, we monitored tumor development in a cohort of NEK1 +/- kat2J mice and wild type mice as they aged." (PMID 21214959, 2011). "Our findings demonstrate that NEK1 promotes tumor progression both in vitro and in vivo." (PMID 42193091, 2026). "The broader implications of these findings are significant, as they suggest that targeting NEK1 could improve the therapeutic index of radiotherapy by selectively enhancing the radiosensitivity of tumor cells while sparing normal tissues." (PMID 41154634, 2025). "Furthermore, we found that NEK1/2/3/7/9/10 mRNA expressions had a trend with higher statistical significance in more advanced tumors based on tumor stage indicators." (PMID 34834441, 2021). "In univariate analyses, local tumor failure was associated with T-stage (p = 0.011), FIGO category (p = 0.006) and Nek1 overexpression (p = 0.028), while only Nek1 overexpression remained an independent adverse prognosticator for local failure in multivariate analyses." (PMID 32429458, 2020). "Whether loss of NEK1 might coexist with β-catenin stabilization, similarly to WT1 alterations, for the survival and proliferation of tumor cells is an open question." (PMID 26317783, 2015).
tumor (continued). "Further studies on whether diminished NEK1 expression leads to tumor formation in humans should be explored." (PMID 21214959, 2011). "In addition, we investigated if Nek1 expression levels could represent a prognostic marker for tumor response and analyzed uterine cervical carcinomas." (PMID 32429458, 2020). "Second, in line with preclinical evidence that fractionated radiation can induce an extensive array of targetable molecules, Nek1 inhibition may be combined with additional targeting strategies against transcription factors, immune and inflammatory responses and tumor cell stemness." (PMID 32429458, 2020). "Differentiating direct from secondary events might require in vivo experiments, with transgenic mice overexpressing NEK1 crossed into the NEK1/kat2J -/- background, where the mice could be observed for rescue of tumor formation and genomic instability phenotypes." (PMID 21214959, 2011). "Correlated increase of TLK1B and pNEK1 T141 with PCa progression was evident from a human PCa-TMA, TRAMP (a PCa mice model) and PDX tumor tissues; all suggested the universality of TLK1>NEK1 signaling in PCa models." (PMID 35582542, 2022). "In bladder cancer, NEK1 is part of a twelve gene tumor score panel used to predict the progression from non-invasive to muscle-invasive disease." (PMID 41154634, 2025). "Similarly, NEK1 T141A overexpressing LNCaP and xenograft tumor remain sensitive to ADT and do not transition to AI growth, which confirms the persistence of TLK1>NEK1 signaling in PCa drug resistance to ADT." (PMID 35582542, 2022). "Although we tried to ensure mechanistically that J54 works via inhibition of the ADT-activated TLK > Nek1>ATR > Chk1 DDR pathway, we cannot rule out that the tumor regression effects that we have observed could be caused by inhibition of some other target." (PMID 32905878, 2020). "Neither is it known whether NEK1 functions as a tumor suppressor like many checkpoint/mitotic kinases (CHK1, Mps1, and BubR1)." (PMID 21214959, 2011). "In PRAD, no significant alteration in mRNA expression of NEK1 was observed, while YAP1 mRNA level was consistently downregulated with respect to the tumor Gleason score." (PMID 33297404, 2020). "By contrast, NEK1, NEK7, and NEK9 expression showed no obvious trend with the tumour grade." (PMID 38706902, 2024). "In addition, mitosis A (NIMA)-related kinase 1 (NEK1), belonging to NEK family, has never yet been reported to be involved in the modulation of mitosis and apoptosis, processes of which are involved in the regulation of tumor progression." (PMID 35083134, 2021).
kidney (2 papers, 2014 to 2023). "After ischemic/oxidative kidney injury, which causes DNA damage, Nek1 expression is upregulated, and a portion of cellular Nek1 moves from cytoplasm to the foci of DNA damage in the nucleus." (PMID 25030234, 2014).
infection (1 paper, 2014). The state of being infected such as from the introduction of a foreign agent such as serum, vaccine, antigenic substance or organism. "Cells were harvested every 24 hours after infection with adenovirus carrying shRNA targeting either Nek1 (Ad-Nek1i) or a control construct, luciferase (Ad-Luci)." (PMID 24970796, 2014). "Expression of Nek1 was significantly reduced by 96 hours after the infection." (PMID 24970796, 2014).
neurodevelopmental disorder (1 paper, 2020). A behavioral and cognitive disorder with onset during the developmental period that involves impaired or aberrant development of intellectual, motor, or social functions. "Other genes, such as GMIP, NEK1, TFPT, CELSR3, and TTC21A, also showed interactions with ASD or other neurodevelopmental disorder-related genes in each gene network in the previous studies." (PMID 33374967, 2020).
NEK1 also shares sentences with these, for which no sentence is quoted: neurodegenerative disease (3 papers); thyroid cancer (2); Arrhythmogenic right ventricular dysplasia (1); ataxia telangiectasia (1); autism spectrum disorder (1); autosomal dominant polycystic kidney disease (1); axial spondylometaphyseal dysplasia (1); bladder carcinoma (1); cancer of the kidney (1); cardiomyopathy (1); cerebellar ataxia (1); cognitive decline (1); connective tissue disorder (1); differentiated thyroid carcinoma (1); Fraser syndrome (1); genetic disorders (1); head and neck squamous cell carcinoma (1); heart malformations (1); hepatocellular carcinoma (1); hereditary colorectal cancer (1); hereditary spastic paraplegia (1); Hydroureter (1); Infertility (1); Kidney Cyst (1); Mohr-syndrome (1); muscular dystrophy (1); neurological disease (1); odontochondrodysplasia (1); pancreatic cancer (1); renal carcinoma (1).
A further 8 diseases each share a sentence with NEK1 in 1 paper.